HOXA1 (homeobox A1)
Diseases named in the same sentence as HOXA1 in open-access papers (continued):
Sharing a sentence is not in itself a finding about the gene and the disease.
cancer (continued). "Thus, although HOXA1 was not differentially expressed in LSCC, the prognostic value of HOXA1 has been highlighted in various human cancers, including in LSCC." (PMID 32296636, 2020). "Previous reports indicated that HOXA1 plays an important role in cancer development." (PMID 26417931, 2015). "The article by Brock and colleagues has firmly established the feasibility of using HOXA1 siRNA-nanoparticles as an effective cancer preventive/therapeutic agent and their delivery into the ducts through the nipple as a means of treating mammary preneoplasias in the preclinical setting." (PMID 25927933, 2014). "However, little was known about whether high HOXA1 expression promotes the radioresistance of cancer cells." (PMID 36119466, 2022). "Taken together, the results of this study demonstrate that HOXA1 has potential to be a predictive marker for radioresistance and post-radiotherapy prognosis that could help to guide individualized treatment in multiple cancer types." (PMID 36119466, 2022). "Hence, HOXA1 could induce radioresistance of cancer cells via inhibition of oxidative phosphorylation." (PMID 36119466, 2022). "Similarly to Satb1 and Hoxa1, Tmeff2 and Enpp2 are up regulated in carcinomas." (PMID 21054883, 2010). "HOXA1, HOXC13 and HOXD10 were significantly correlated with the cancer hallmarks driving oral carcinogenesis." (PMID 40676709, 2025). "High expression levels of LincRNA H19, miR-675, MRP3, HOXA1, and MMP16 in cancer tissues correlated with advanced disease stages and poorer survival rates." (PMID 39267845, 2024). "HOXA1 is targeted by miR‐218 and miR-216b-5p and directly modulates the expression of ENO1 and PGK1, thus promoting glycolysis and inducing cancer progression." (PMID 38311789, 2024). "HOXA1 was more frequently expressed in smaller tumors (≤2.0 cm), particularly in IDC (P<0.0001), and in early-stage cancers (P<0.0001)." (PMID 39267845, 2024). "Conversely, suppression of HOXA1 results in high expression of E-cadherin and low expression of Snail and MMP-3 in PCa cells, indicating a potential role in inhibiting cancer progression." (PMID 38311789, 2024). "Similar to our in vitro results, the expression of HOTAIRM1 and HOXA1 were up-regulated in the recurred cancer patient group, supporting our conclusion that HOTAIRM1 and HOXA1 are prospective indicators for tamoxifen resistance." (PMID 32284737, 2020). "The genes selected using this method included NCOA3, HOXA1, FOLR1, SOCS1, and PIK4CA, which showed similar expression patterns related to survival in patients with cancer." (PMID 29854877, 2018). "We thus identified two loci, HOXA1 and TMEFF2, that appear to have an “intermediate” role in cancer development in the lung as well as the breast." (PMID 21731750, 2011). "Notably, HOXA1, HOXC13 and HOXD10 were strongly correlated with cancer hallmarks, indicating their regulatory role in carcinogenesis." (PMID 40676709, 2025). "HOXA1, HOXD10 and HOXC13 are strongly correlated with cancer hallmarks." (PMID 40676709, 2025). "The gene set enrichment analysis (GSEA) results indicated that HOXA1 and HOXA11 were involved in immune responses pathways and participated in the activation of a variety of classic signaling pathways related to the progression of human cancer." (PMID 34606634, 2021). "Although these studies suggest that upregulation of HOXA1 promotes cancer progression, the role of HOXA1 in determining the biological properties of malignant tumors is not fully understood, nor has the correlation between HOXA1 expression and cancer radioresistance been reported." (PMID 36119466, 2022). "Unlike other cancers, knockdown of KDM3A does not affect HOXA1 expression or cell cycle distribution in MM cells." (PMID 26728187, 2016).
heart disease (3 papers, 2019 to 2024). "Accordingly, we successfully constructed a hoxa1a-null model with a cardiac disease pattern which occurred in human HOXA1-associated heart malformation." (PMID 37508332, 2023). "Previous studies report that Gata4 and Gata6 are essential for heart development, and Hoxa1 mutant mice develop heart disease, suggesting a previously uncharacterized association between Hoxa1 and Gata4/6." (PMID 31147716, 2019). "Moreover, a previous study reported that Hoxa1 mutant mice exhibit phenotypes indicative of heart disease, confirming a direct association of Hoxa1 with endodermal organ development." (PMID 31147716, 2019). "HOXA1 not only plays a crucial role in heart disease regulation but is also involved in joint-related diseases, specifically through its influence on apoptosis." (PMID 38311789, 2024). "In recent years, several studies have provided evidence of the involvement of HOXA1 expression in heart disease, particularly in congenital heart defects (CHD)." (PMID 38311789, 2024).
genetic disorders (1 paper, 2024). "For instance, mutations in HOXA1 have been linked to a group of genetic disorders referred to as "HOXA1-related syndromes"." (PMID 38311789, 2024).
hematological disorders (1 paper, 2023). "Eight of these lncRNAs have already demonstrated an involvement in hematological disorders: HOTAIRM1 gene is adjacent and antisense to the transcription start site of HOXA1, and its transcription is initiated from the shared promoter segment embedded in a CpG island between the two genes." (PMID 37486375, 2023).
infection (1 paper, 2026). The state of being infected such as from the introduction of a foreign agent such as serum, vaccine, antigenic substance or organism. "At 8 h post-infection, NCC-PCs showed significant downregulation of a number of genes with a notable exception of HOXA1, which was significantly upregulated." (PMID 41541694, 2026).
movement disorder (1 paper, 2023). Neurological conditions resulting in abnormal voluntary or involuntary movement, which may impact the speed, fluency, quality and ease of movement. "This movement disorder in fish also happens in BSAS patients with HOXA1 mutations who present motor development delay." (PMID 37508332, 2023).
HOXA1 also shares sentences with these, for which no sentence is quoted: adenocarcinoma (2 papers); colon cancer (2); hearing loss (2); squamous cell carcinoma (2); squamous cell lung carcinoma (2); 22q11.2 deletion syndrome (1); acute promyelocytic leukemia (1); adult T-cell leukemia/lymphoma (1); Andersen syndrome (1); Athabascan Brainstem Dysgenesis Syndrome (1); Athabaskan brainstem dysgenesis syndrome (1); atypical ductal hyperplasia (1); auricular malformation (1); bilateral deafness (1); breast-invasive carcinoma (1); cervical squamous cell carcinoma (1); chronic pancreatitis (1); colorectal cancer (1); congenital heart disease (1); depression (1); developmental delay (1); diffuse large B-cell lymphoma (1); Down syndrome (1); ductal carcinoma in situ (1); endocervical adenocarcinoma (1); epilepsy (1); hand-foot-genital syndrome (1); head and neck tumors (1); Heart Malformation (1); Hepatitis (1).
A further 27 diseases each share a sentence with HOXA1 in 1 paper.